AURKA (aurora kinase A)
Diseases named in the same sentence as AURKA in open-access papers (continued):
Sharing a sentence is not in itself a finding about the gene and the disease.
cervical cancer (20 papers, 2010 to 2026). A primary or metastatic malignant neoplasm involving the cervix. "We further investigate the associations of AURKA SNPs with recurrence and survival events of cervical cancer patients." (PMID 33967624, 2021). "Some other studies have shown DSG2, PLOD2, ANLN, AURKA, and AR genes might be key genes associated with cervical cancer progression." (PMID 41266827, 2025). "AURKA was overexpressed and associated with lymph-node metastasis in cervical cancer patients." (PMID 39060960, 2024). "In addition, they found that increased expression of Aurora kinase A (AURKA) was associated with poor prognosis in patients with cervical cancer." (PMID 34722295, 2021). "Furthermore, genetic variants of Aurora A kinase (AURKA) have been shown to be associated with a radiotherapy-induced early adverse reaction in patients with cervical cancer." (PMID 25695263, 2015). "AURKA overexpression may promote c-Myc oncogenic effects and cause its increased expression 35, which is associated with the development of a variety of cancers, including gynecological malignancies such as ovarian, endometrial and cervical cancers 36-38." (PMID 33967624, 2021). "The literature review suggested that AURKA was an enhanced potential target for cervical cancer treatment." (PMID 35409328, 2022). "When time interval was included to correlate AURKA SNPs with prognosis, recurrence-free survival and overall survival were assessed in cervical cancer patients." (PMID 33967624, 2021). "The in vivo role of Asp132-cleavage of AURKA on the anticancer efficacy of Taxol was determined in a Matrigel Plug tumor xenograft model with human cervical carcinoma HeLa cells stable expressing AURKAWT, AURKAD132A, or YFP vector in the presence or absence of Taxol for 8 days." (PMID 38994036, 2024). "Functional analysis showed that inhibition of AURKA could reduce the proliferation and invasion of cervical cancer cells in vitro." (PMID 34722295, 2021). "Although AURKA SNPs may have an impact on amino acid changes, this study did not seem to show that AURKA SNPs have an influence on the development of cervical cancer." (PMID 33967624, 2021). "Neither AURKA rs6024836 nor other AURKA SNPs are associated with recurrence and mortality events of cervical cancer patients." (PMID 33967624, 2021). "Therefore, we conducted this study to delineate the involvement of AURKA in the cervical carcinogenesis and clinical variables and patient survival of cervical cancer." (PMID 33967624, 2021). "Pharmacological inhibition of AURKA promotes the chemosensitivity of cervical cancer cells." (PMID 34332577, 2021). "Oncogenic kinases and methyltransferases including AURKA, AURKB, ESCO1, NEK6, and PRMTs that promote carcinogenesis are notably upregulated in cervical cancer." (PMID 41562705, 2026). "The TOP2A, AURKA and CCNA2 in cervical cancer were significantly increased, while IVL, KRT1, and IGFBP5 were significantly decreased, compared with normal tissues, which was consistent with the screening results." (PMID 39060960, 2024). "The expression of these hub genes were verified through TCGA, GEPIA, qRT-PCR, and immunohistochemistry, and it was found that TOP2A, AURKA as well as CCNA2 were overexpressed and IGFBP5 was low expression in cervical cancer." (PMID 39060960, 2024). "TOP2A, AURKA and CCNA2 were overexpressed in cervical cancer, while IVL and IGFBP5 were low expression in cervical cancer." (PMID 39060960, 2024). "Two of the genes of this signature, AURKA and UBE2C, were validated in human breast and cervical cancer as potential biomarkers of malignancy." (PMID 20630075, 2010). "The antibody CAB001454 did not detect AURKA in normal cervix tissues, and showed moderate intensity staining in cervical cancer tissues, with the proportion of stained cells ranging from 25 to 75%." (PMID 39060960, 2024).
cervical cancer (continued). "The results showed that the expression of TOP2A, AURKA and CCNA2 were statistically increased in cervical cancer cell, while the expression of IGFPB5 was statistically decreased in cervical cancer cell, which was consistent with the results of GEO dataset and TCGA database." (PMID 39060960, 2024). "It was found that TOP2A, AURKA, CCNA2 and IGFBP5 could be all potential tumor markers for cervical cancer." (PMID 39060960, 2024). "Although MAD2L1, TOP2A, AURKA, and ASPM were reported in various research findings, they may play a remarkable role in the survival of cervical cancer." (PMID 36723760, 2023). "After dividing cervical neoplasias into invasive cancer and precancerous subgroups, AURKA SNPs still did not participate in the occurrence of cervical cancer." (PMID 33967624, 2021). "In conclusion, AURKA SNPs rs2273535, rs6024836, rs2064863 and rs1047972 does not seem to be involved in the occurrence of cervical cancer in Taiwanese women." (PMID 33967624, 2021). "In the Kaplan-Meier curve univariate analysis model, AURKA rs6024836 was not related to recurrence-free survival and overall survival of cervical cancer patients." (PMID 33967624, 2021). "To date, no reports have investigated the relationships between AURKA SNPs and the development of cervical cancer." (PMID 33967624, 2021). "So far, no study explores the relationship of AURKA SNPs and the survival of cervical cancer patients." (PMID 33967624, 2021). "These previous findings and the results of the present analysis suggest that TTK, AURKA and BRCA2 may participate in the progression of cervical cancer." (PMID 25695263, 2015). "This study showed that TOP2A, AURKA, CCNA2 and IGFBP5 screened through bioinformatics analysis were significantly differentially expressed in cervical cancer samples compared with normal samples, which might be biomarkers of cervical cancer." (PMID 39060960, 2024). "Indeed, knockdown or inhibition of PLK1, CDK1, AURKA, MELK, and NEK2 resulted in reduction or repression of metastatic potential and invasiveness of various cancer types, including mCRPC and cervical cancer." (PMID 34680307, 2021). "Therefore, miR-149-5p may act as key modulator in the oncogenic role of hsa_circ_0075341 in cervical cancer, by binding 3’-UTR region of AURKA." (PMID 34722295, 2021). "In conclusion, tumor size and pelvic lymph node status rather than AURKA SNPs were the most obvious independent parameter that could significantly predict 5 years survival rate in Taiwanese women with cervical cancer." (PMID 33967624, 2021). "In the present paper we identified six putative biomarkers (AURKA, DTL, HMGB3, KIF2C, NEK2, and RFC4) which should be further tested to separate indolent HPV related cervical infections from progressive CIN III lesions and for early diagnosis of cervical cancer." (PMID 26701206, 2016). "However, interestingly, the TCGA database and GEPIA online website analysis showed that TOP2A, AURKA, CCNA2 and IVL were overexpressed and IGFBP5 was low expression in cervical cancer, and there was no statistical difference in the expression of KRT1 in cervical cancer tissue and normal tissue." (PMID 39060960, 2024).
triple-negative breast carcinoma (20 papers, 2016 to 2025). An invasive breast carcinoma which is negative for expression of estrogen receptor (ER), progesterone receptor (PR), and human epidermal growth factor receptor 2 (HER2). "We initially observed that in triple-negative breast cancer, where AURKA is typically overexpressed, the short isoform is predominant and this correlates with faster relapse times of patients." (PMID 37384380, 2023). "Last, we discover that the roles of the AURKA/ATP5F1A/ATP5F1B nexus depend on the specific metabolic propensity of triple-negative breast cancer cell lines, where they correlate with cell fate." (PMID 37386025, 2023). "In docetaxel-resistant and paclitaxel-resistant triple-negative breast cancer cells, aurora kinase A (AURKA) is highly expressed in the cells, where it mediates TGF-β-induced EMT and produces resistance to these drugs." (PMID 35684449, 2022). "Inhibition of AURKA affect the vasculogenic mimicry formation of CSCs in triple negative breast cancer." (PMID 35059393, 2021). "Other substrates such as c-Myc and AURKA have important roles in tumorigenesis by promoting cancer cell survival and migration and AURKA has been found overexpressed in a series of triple negative breast carcinomas." (PMID 27409838, 2016). "Interestingly, AURKA has demonstrated that elevated PD-L1 expression and triggers PD-L1-mediated immune suppression in triple-negative breast cancer." (PMID 38643462, 2024). "Altogether, these data further support the direct role of AURKA, ATP5F1A, and ATP5F1B within a potential metabolic nexus in triple-negative breast cancer cells." (PMID 37386025, 2023). "AURKA was essential for mediating TGF-beta induced plasticity and chemoresistance in triple-negative breast cancer." (PMID 34336648, 2021). "In triple-negative breast cancer models, KLT effectively blocked cell cycle progression at the G2/M phase by downregulating CDK1, CDK2, and CHEK1, inhibiting CDC25A, CDC25B, MELK, and AURKA activity, suppressing mitosis, and inducing apoptosis." (PMID 41164166, 2025).
acute myeloid leukemia (19 papers, 2011 to 2025). Acute myeloid leukemia (AML) is a group of neoplasms arising from precursor cells committed to the myeloid cell-line differentiation. "The CRBN-recruiting PROTAC preferentially degraded mitotic pools of AURKA, while the cIAP1 PROTAC was better at degrading interphase AURKA in acute myeloid leukaemia cells." (PMID 40316744, 2025). "The siTCR design also retained the sensitivity and efficacy of the original TCR design, and was effective against AURKA-positive acute myeloid leukaemia (AML) cells, including side-population cells." (PMID 27271876, 2016). "First of all, alisertib – a specific Aurora kinase A inhibitor currently being evaluated in clinical trials in various neoplastic conditions, including acute myeloid leukemia demonstrated very good preclinical activity when we tested it in HMC-1 cells and in neoplastic MCs from MCL patients." (PMID 36894973, 2023). "The CRBN‐based dAurA383 preferentially degrades the highly abundant mitotic AURKA, while cIAP‐based dAurA450 degrades the lowly abundant interphase AURKA in acute myeloid leukemia (AML) cells." (PMID 35652200, 2022). "In acute myeloid leukemia (AML), AURKA indirectly activates the NF-κB pathway by phosphorylating TIFA at T9." (PMID 39334449, 2024). "The combination of dAurA383 and dAurA450 sequentially degrades the mitotic and interphase AURKA, impairs AML proliferation, relieves the hook effect, and abrogates acute myeloid leukemia stem cells." (PMID 35652200, 2022). "Furthermore, in the carcinogenesis of acute myeloid leukemia (AML), a novel functional link has been revealed between AEG-1/MTDH and Aurora A kinase (AURKA) with regard to Akt1 activation." (PMID 25009642, 2014). "For example, a PROTAC consisting of alisertib, a clinically used ATP-competitive inhibitor of AURKA, and thalidomide, which induces protein degradation via cereblon-containing ubiquitin ligase, results in proteolysis of AURKA and arrest of the cell cycle in MV4-11 human acute myeloid leukemia cells." (PMID 34944109, 2021). "Both compounds very effectively reduced expression of BTK within 4 h in acute myeloid leukemia (AML)-derived MOLM-14 cells with little effect on other potential PROTAC targets investigated, including AURKA." (PMID 32924028, 2020). "Although the precise mechanism by which TUG1 regulates AURKA in HCC was not demonstrated in the study, consistent evidence showed that TUG1 positively modulates AURKA in adult acute myeloid leukemia (AML)." (PMID 39598228, 2024).
endometrial cancer (17 papers, 2011 to 2026). Primary or metastatic malignant neoplasm involving the endometrium (mucous membrane that lines the endometrial cavity). "Overexpression of AURKA was associated with tumor grade and histological type in endometrial cancer tissues in χ2 tests and a tendency for this association remained in logistic regression analysis, but this was not significant (data not shown)." (PMID 25625960, 2015). "To investigate the role of AURKA in endometrial cancer, we evaluated the association of immunohistochemical expression of AURKA with clinicopathological factors." (PMID 25625960, 2015). "In this study, we found an association of overexpression of AURKA with clinicopathological factors in endometrial cancer." (PMID 25625960, 2015). "In summary, our data on endometrial carcinoma show that overexpression of AURKA is strongly associated with tumor grade and histological type, and that there is a correlation between expression of AURKA and sensitivity to paclitaxel." (PMID 25625960, 2015). "Collectively, these data show that JAG2, AURKA, PGK1, and HRPT1 have the potential to be used independently as diagnostic, prognostic, or treatment biomarkers in endometrial cancer." (PMID 30679932, 2019). "AURKA inhibition in endometrial cancer cell lines significantly decreased cell growth, invasion and migration (P<0.05), and increased chemosensitivity to paclitaxel." (PMID 25625960, 2015). "We screened endogenous AURKA expression in a panel of four endometrial cancer cell lines: HEC-108 (poorly-differentiated), HEC-1B and HHUA (moderately-differentiated), and SNG-M (well-differentiated)." (PMID 25625960, 2015). "Our results showed that specific inhibition of AURKA by siRNA suppressed endometrial cancer cell growth, migration and invasion." (PMID 25625960, 2015). "Although AURKA is a potential new oncogenic target, the role of this protein in endometrial cancer is unclear." (PMID 25625960, 2015). "Immunohistochemistry showed overexpression of AURKA in endometrial cancer tissues compared with normal endometrium, indicating that upregulation of AURKA is a frequent abnormality in endometrial cancer." (PMID 25625960, 2015). "Overexpression of AURKA occurred at a significantly higher rate in endometrial carcinoma than in normal endometrial tissues (49 vs. 3%)." (PMID 25625960, 2015). "In addition, the data also shows that the higher expression of AKT1, GTSE1, BIRC5, AURKA, and KNSTRN is significantly associate with poor prognosis of endometrial cancer." (PMID 31781484, 2019). "Moreover, the data also shows that the higher expression of AKT1, GTSE1, BIRC5, AURKA, and KNSTRN is significantly associate with poor prognosis of endometrial cancer." (PMID 31781484, 2019). "Combination treatment using AURKA inhibitors and paclitaxel may be particularly effective for cases of endometrial cancer that are resistant to conventional treatment." (PMID 25625960, 2015). "Therefore, these in vivo data indicate enhanced antitumor activity of AURKA siRNA and paclitaxel combination in endometrial cancer." (PMID 25625960, 2015). "AURKA is a promising therapeutic target in endometrial cancer and the combination therapy with AURKA inhibitors and paclitaxel could be effective for endometrial cancer that is resistant to conventional treatment and has a poor prognosis." (PMID 25625960, 2015). "The aim of this study was to clarify the significance of AURKA expression in endometrial cancer." (PMID 25625960, 2015). "AURKA was expressed mainly in the nucleus in normal endometrium and endometrial cancer tissues." (PMID 25625960, 2015). "The role AURKA may play as a diagnostic biomarker in endometrial cancer has not been well studied, although it has shown promising results in other cancer types." (PMID 30679932, 2019). "However, only a few reports have described a role for AURKA in endometrial cancer." (PMID 25625960, 2015).
endometrial cancer (continued). "They proposed that the jagged canonical Notch ligand 2 (JAG2), Aurora kinase A (AURKA), phosphoglycerate kinase 1 (PGK1), and hypoxanthine phosphoribosyltransferase 1 (HRPT1) could be used independently as diagnostic, prognostic, or treatment biomarkers in endometrial cancer." (PMID 34322276, 2019). "We selected the six hub genes (GTSE1, BIRC5, AURKA, PBK, KNSTRN, and PSMB10) and AKT1 to evaluate gene expression values in endometrial cancer using IHC." (PMID 31781484, 2019). "We have determined that there is a significant elevation of JAG2, HPRT1, AURKA, and PGK1 expression in endometrial cancer." (PMID 30679932, 2019).
esophageal cancer (17 papers, 2010 to 2025). A primary or metastatic malignant neoplasm involving the esophagus. "Polymorphism rs1047972, one of the most investigated variants in AURKA gene, showed significant association with the increased esophagus cancer risk as well as with gastric cancer risk and progression." (PMID 31521144, 2019). "For esophageal cancer, the AurkA Phe31-Ile polymorphism has previously been associated with tumor progression." (PMID 29560108, 2018). "Moreover, it has been shown that the AurkA Phe31-Ile polymorphism enhances esophageal cancer progression." (PMID 29560108, 2018). "We analysed the correlation of AURKA or AURKB with BRD4 in oesophageal cancer using the GEPIA web‐based tool." (PMID 32954665, 2020). "In conclusion, our study explored the anti‐proliferative effect of JQ1 in oesophageal cancer cells and identified the regulatory mechanism involved in their senescence through the up‐regulation of p21 and down‐regulation of AURKA and AURKB." (PMID 32954665, 2020). "Concordantly, an increased frequency of the heterocygous AurkA genotype in esophageal carcinomas has been found which has been attributed to enhanced tumor progression." (PMID 29560108, 2018). "Therefore, exploring the relationship between AURKA and esophageal cancer and its mechanism might help to provide a new target for the treatment of esophageal cancer." (PMID 32546690, 2020). "Bioluminescence imaging results indicated ZNF468 significantly increased the pulmonary metastatic burden of KYSE510 cells in oesophageal cancer, while the pro‐metastatic effect of ZNF468 was markedly diminished under conditions of AURKA knockdown." (PMID 40702875, 2025). "In our current investigation, we found that AURKA exhibited significantly elevated expression levels and was correlated with OS and DSS across multiple cancer types, including esophageal carcinoma (ESCA)." (PMID 37965456, 2023). "Together, our data suggested that BRD4 inhibition induced cellular senescence by down‐regulating AURKA and AURKB in human oesophageal cancer cells." (PMID 32954665, 2020). "Finally, using the TCGA database, we determined that the expression of AURKA and AURKB in oesophageal cancer tissues is much higher than those in the normal tissues." (PMID 32954665, 2020).